BCL2 (BCL2 apoptosis regulator)
Diseases named in the same sentence as BCL2 in open-access papers (continued):
Sharing a sentence is not in itself a finding about the gene and the disease.
mycosis fungoides (4 papers, 2014 to 2026). Classical mycosis fungoides is the most common type of mycosis fungoides (MF), a form of cutaneous T-cell lymphoma, and is characterized by slow progression from patches to more infiltrated plaques and eventually to tumors. "In mycosis fungoides tumor cells, some apoptosis-related genes, such as Bcl-2 and Bax, have been identified as STAT3 target genes." (PMID 25092271, 2014). "In this case, the evolution from a CD20-negative, CD30-negative profile during the initial diagnosis of mycosis fungoides to subsequent biopsies with a clear immunohistochemical profile (CD20+, MUM1+, and BCL2+) and nodular clinical presentation supports a final diagnosis of PCDLBCL-LT." (PMID 40918840, 2025).
myocarditis (4 papers, 2017 to 2025). Myocarditis is a condition that is characterized by inflammation of the heart muscle (myocardium). "The expression levels of Bax were positively correlated with cardiomyocyte apoptosis in myocarditis, but the opposite was true for Bcl-2." (PMID 29556195, 2018).
nervous system cancer (4 papers, 2021 to 2025). A primary or metastatic malignant neoplasm involving the nervous system. "Neural tumors such as schwannoma and neurofibroma can show focal positivity for BCL2 and CD34 and strong positivity for S100 protein." (PMID 34211794, 2021). "The positive expression of bcl-2 seen in neural neoplasms could be due to the fact that these tumors stem from the neural crest cell lineage, which also expresses bcl-2." (PMID 34200924, 2021). "Although OFM lacks specific immunohistochemical markers, IHC is useful for excluding other myxoid lesions—S-100 helps rule out neural tumours, while CD34, STAT6, and BCL2 assist in excluding myxoid solitary fibrous tumour." (PMID 41283480, 2025).
Odontogenic tumor (4 papers, 2017 to 2025). "The expression of Bcl-2 in the cystic epithelium was also compared with the neoplastic epithelium of odontogenic tumors." (PMID 40818142, 2025).
oral lichen planus (4 papers, 2012 to 2017). Oral lichen planus is a chronic inflammatory oral condition of unknown aetiology characterized by T-cell-mediated chronic immune response and abnormal epithelial keratinization cycle. "Bcl-2 has been identified as a key regulator of apoptosis, which is overly expressed in OLK and oral lichen planus." (PMID 29088845, 2017).
parasitic infection (4 papers, 2011 to 2021). "Among these, we highlight miR-16-5p given its significant gradual upregulation during the course of P. falciparum infection and the role of its target genes in apoptosis, in particular BCL2 which is downregulated during symptomatic parasitemia." (PMID 33037226, 2020).
plasmacytoma (4 papers, 2009 to 2025). Plasmacytoma is a localized mass of neoplastic monoclonal plasma cells that represents approximately 5% of all plasma cell neoplasms. "The tumor cells were lambda light chain restricted and positive for CD45, weakly positive for CD79a and negative for CD20, CD30, CD10, CD5, BCl-2, Bcl-6, Pax5 and S100, and consistent with anaplastic plasmacytoma." (PMID 19495405, 2009). "Although we have no indication about the eventual supplemental hits supporting the growth of plasmacytoma in aged BCL2 mice from our current study, acquired genetic or epigenetic anomalies are likely since no tumor arises in young mice, whatever the BCL2 expression dosage." (PMID 36358756, 2022). "Mice expressing BCL2 under the control of the IGH enhancer (Eμ) have increased accumulation of BCL2 protein in B cells, dramatically increased numbers of mature B cells and GC B cells, and develop low-incidence pre-B lymphomas, immunoblastic lymphomas and plasmacytomas." (PMID 33914737, 2021).
salivary gland neoplasms (4 papers, 2008 to 2012). Tumors of the SALIVARY GLANDS. "In the studies with TUNEL in salivary gland neoplasms, apoptotic activity was inversely associated with Bcl-2 immunoexpression." (PMID 22313995, 2012). "Altogether, the evidence points to Bcl-2 as an important factor in the salivary gland neoplasms pathogenesis and as a possible molecular target in salivary gland tumour treatment in the future." (PMID 22313995, 2012). "Bcl-2 and Bax proteins are expressed in most of the salivary gland neoplasms investigated, but Bcl-2 positivity was found in a lower percentage of mucoepidermoid carcinomas." (PMID 22313995, 2012). "The bcl-2 oncoprotein is a potent inhibitor of apoptosis and is overexpressed in a wide variety of malignancies, including salivary gland tumors." (PMID 21034499, 2010). "It was reported, using the 3'-end DNA labeling method (TUNEL), that in salivary gland neoplasms apoptosis is inversely associated with Bcl-2 expression, but not related to Bax expression." (PMID 22313995, 2012). "This study was aimed to investigate the immunoexpression of mdm2 oncoprotein, p27Kip1 tumor suppressor protein as well as bcl-2 anti-apoptotic protein in Warthin's tumor as a trial to clarify the possible role of these families in the pathogenesis of this unique tumor of salivary glands." (PMID 19445705, 2009).
serous ovarian cancer (4 papers, 2020 to 2025). "Combined MEK and Bcl‐2/xL inhibition was also shown to be effective in high‐grade serous ovarian cancer patient‐derived xenograft models." (PMID 34861096, 2022). "Similarly, a study on serous ovarian cancer cell lines demonstrated that PIK3R1 downregulation induced the expression of antiapoptotic BCL2, as well as genes involved in cell cycle progression (CCNB1) and metastasis (MMP9 and VEGFA)." (PMID 39858051, 2025).
soft tissue sarcoma (4 papers, 2020 to 2023). A malignant neoplasm arising from muscle tissue, adipose tissue, blood vessels, fibrous tissue, or other supportive tissues excluding the bones. "Despite variable expression of Bcl-2 in soft tissue sarcomas, the anti-Bcl-2 therapy has been studied with promising results." (PMID 37720343, 2023). "In a panel of soft-tissue sarcoma cell lines induced into senescence by irradiation, BCL-2 or BCL-xL were differentially increased depending on the cell line, but the cells were all comparably sensitive to senolysis by venetoclax or navitoclax, irrespectively of BCL-2 and BCL-xL expression levels." (PMID 36128715, 2022).
thymic lymphoma (4 papers, 2008 to 2014). "Here we report a striking synergistic cooperation between p27 deficiency and Bcl-2 in thymic lymphoma development." (PMID 18382684, 2008). "P27 −/− Lck-Bcl-2 mice were highly susceptible to thymic lymphomas with complete penetrance by 60 weeks of age." (PMID 18382684, 2008). "We have previously shown that ATN-224, a copper chelator drug, induces cell death in murine thymic lymphoma cells transfected with Bcl-2." (PMID 24788952, 2014). "Treatment with ATN-224 resulted in cell death in parental murine thymic lymphoma cells and those transfected with Bcl-2 that are apoptosis resistant." (PMID 24788952, 2014). "As a positive control for Deltex1 and Hes1 expression, we used the immature DN S49 thymic lymphoma cells (lane 5) that endogenously express Bcl-2 and active Notch1." (PMID 22319533, 2012). "This high penetrance contrasts with a one year incidence of <5% of thymic lymphoma in Lck-Bcl-2 or p27 −/− mice alone." (PMID 18382684, 2008). "Only in the presence of both Bcl-2 and ICN, PD1.6 thymic lymphoma cells become resistant to glucocorticoid (GC)-induced apoptosis." (PMID 22319533, 2012). "While the mature 2B4 T hybridoma cells express basal Bcl-2 levels, the immature DP PD1.6 thymic lymphoma cells barely express any Bcl-2 or Bcl-XL." (PMID 22319533, 2012). "However, these genes were not induced in Bcl-2-negative DP PD1.6 thymic lymphoma cells overexpressing ICN." (PMID 22319533, 2012).
vascular dementia (4 papers, 2012 to 2025). A degenerative vascular disorder affecting the brain. "We confirmed that the expression of Bcl-2 was down-regulated in the hippocampus of vascular dementia rats, while LC3II and Beclin-1 were significantly increased." (PMID 36767264, 2023). "In addition, the enhanced density of Bcl-2-immunopositive neurons and the suppression of AChE in the area just mentioned were also observed in accompany with the increased spatial memory in animal model of vascular dementia." (PMID 22952555, 2012).
acute lung injury (3 papers, 2020 to 2022). A condition of lung damage that is characterized by bilateral pulmonary infiltrates (pulmonary edema) rich in neutrophils, and in the absence of clinical heart failure. "The acute lung injury (ALI) mouse model was successfully induced by smoke inhalation, as confirmed by the aberrantly modified cell numbers of red blood cells and neutrophils counts, increased levels of TNF-α, IL-1β, Bax, caspase-7, caspase-3, and decreased Bcl-2 content in lung tissues." (PMID 35152840, 2022).
acute respiratory distress syndrome (3 papers, 2022 to 2024). Progressive and life-threatening pulmonary distress in the absence of an underlying pulmonary condition, usually following major trauma or surgery. "Similarly, HSP70 overexpression inhibited caspase 3, 8, 9, APAF-1 and Bcl2 activation, preventing Acute Respiratory Distress Syndrome (ARDS) induced by cecal ligation and puncture in rats." (PMID 38339194, 2024). "Additionally, an increased ratio of BCL-2 to the proapoptotic protein BCL2-associated X (BAX) has been measured in fibroblasts isolated from patients with nonresolving fibroproliferative acute respiratory distress syndrome (ARDS) compared with resolving ARDS." (PMID 36752201, 2023).
adult T-cell leukemia/lymphoma (3 papers, 2018 to 2025). A peripheral (mature) T-cell neoplasm linked to the human T-cell leukemia virus type 1 (HTLV-1), adult T-cell leukemia/lymphoma is endemic in several regions of the world, in particular Japan, the Caribbean, and parts of Central Africa. "Combination therapies with BCL-2/BCL-xL inhibitors, targeting the intrinsic pathway, and JAK inhibitor ruxolitinib have demonstrated synergy in pre-clinical models of adult T-cell leukemia lymphoma and T-ALL." (PMID 29682185, 2018).
age-related hearing loss (3 papers, 2010 to 2022). "In the present study, we examined the role of Bcl-2 gene in age-related hearing loss." (PMID 20637089, 2010).
Allergy (3 papers, 2018 to 2025). An allergy is an immune response or reaction to substances that are usually not harmful. "Most importantly, higher Bcl-2 content within key effector cells implies survival advantage with the potential to mount abnormal responses that may give rise to the manifestations of allergy." (PMID 38067164, 2023). "Importantly, we found that allergy immunotherapy increased in expression of ZO-1and E-cadherin without a low apoptosis of airway epithelial cells, resulting in increasing expression of anti-apoptotic Bcl-2 and inhibition of caspase-3." (PMID 29784924, 2018). "In summary, this study suggests the existence of differences in various immunological parameters between different allergies and non-allergic children, the most noticeable being the survival advantage acquired in allergic individuals, through higher Bcl-2 expression in T and B cells." (PMID 38067164, 2023).
amyloidosis (3 papers, 2022 to 2025). A disorder characterized by the localized or diffuse accumulation of amyloid protein in various anatomic sites. "Regarding the Bcl-2, increased levels are well described in AD brains and in amyloid containing brain regions of mice overexpressing APP." (PMID 35810220, 2022).
Androgenic alopecia (3 papers, 2022 to 2025). "Previous researches reveal that EGCG ameliorates androgenic alopecia by selectively inhibiting 5α-reductase activity, and up-regulating phosphorylated Erk and Akt and increasing the Bcl-2/Bax ratio on DPCs." (PMID 37454125, 2023).
aneurysm (3 papers, 2021 to 2023). Bulging or ballooning in an area of an artery secondary to arterial wall weakening. "It is possible that this regulatory interaction may be recapitulated in aneurysms in general, since lower BCL2 expression has been associated with VSMCs in a variety of aneurysms, including abdominal and thoracic aortic and intracranial." (PMID 36066968, 2022). "Based on these findings, we speculate that the BCL-2-mediated ‘intrinsic’ apoptosis pathway might widely function in various aneurysmal diseases, promoting VSMCs phenotype switch, thus might be a novel therapeutic target for aneurysm prevention and treatment." (PMID 34895131, 2021). "We explored whether elimination of stress-induced premature senescent cells by BPTES, independent of the BCL2 pathway, could still inhibit the occurrence and development of aneurysms." (PMID 37196124, 2023).
angiosarcoma (3 papers, 2011 to 2022). A malignant tumor arising from the endothelial cells of the blood vessels. "In the present study, NECTIN4 knockdown downregulated BCL-2 and upregulated BAX in angiosarcoma cell lines and induced apoptosis." (PMID 35256687, 2022). "The data therefore confirm the established oncogenic roles for proteins like Akt, survivin, Bcl-2 and ERK in angiosarcomas and expand the pharmacological utility of specific inhibitors to murine VEGF-dependent angiosarcomas." (PMID 31004117, 2019). "MS1 VEGF angiosarcoma cells exhibit VEGF-dependent tumorigenicity and proteins such as Akt, ERK, Bcl-2 and survivin are known ‘VEGF-effectors’." (PMID 31004117, 2019). "Because NECTIN4 knockdown also decreased Akt and Src phosphorylation, we speculate that these signals are involved in regulation of BCL-2 and/or BAX by NECTIN4 and affects tumor progression of angiosarcoma." (PMID 35256687, 2022). "Expression of Akt, ERK, Bcl-2 and survivin was readily detected in MS1 VEGF angiosarcoma cells." (PMID 31004117, 2019).
Azoospermia (3 papers, 2020 to 2025). Absence of any measurable level of sperm,whereby spermatozoa cannot be observed even after centrifugation of the semen pellet. "Some target genes of the downregulated miRNAs, such as ACVR2A, CCND1, CCNE2, HMGA2, BMI1, NR2C2 and BCL2, have been associated with gonadal development, and germ cell maintenance through different pathways which could be relevant to the molecular mechanisms affected in KS patients with azoospermia." (PMID 32651451, 2020). "Meanwhile, RT-qPCR results showed that transfected miR-143-3p mimic into Sertoli cells significantly inhibited the expression of proliferating cell nuclear antigen (PCNA) and B cell leukemia/lymphoma 2 (BCL2), which are markers of azoospermia and cell proliferation." (PMID 37240155, 2023).
benign prostatic hyperplasia (3 papers, 2024). A non-cancerous nodular enlargement of the prostate gland. "Increased Bcl-2 expression shows an apoptotic mechanisms deregulation that promotes prostatic hyperplasia." (PMID 39273277, 2024). "Furthermore, compared to neighbouring non-cancerous tissues and benign prostatic hyperplasia, Bcl2 gene expression is elevated in PCa tissues." (PMID 39554609, 2024).
Chagas disease (3 papers, 2021 to 2024). A parasitic infection caused by Trypanosoma cruzi. "We identified Bcl2, Gsk3, Nfat5, and Nfatc1 as key players in Chagas disease pathogenesis, and our bioinformatics analysis identified 15 signaling pathways related to Chagas disease development." (PMID 39770386, 2024).
chronic cystitis (3 papers, 2009 to 2023). Recurrent infections of the urinary bladder. "We evaluated and compared COX-2 and Bcl-2 expression in CG, chronic cystitis (CC), and primary vesicle adenocarcinoma (ADC) tissues." (PMID 24387269, 2014). "Moreover, we observed that serpina3n overexpression significantly reversed the decrease in mechanical withdrawal threshold in the cystitis models, as well as the decrease in expression levels of Bcl-2 and the increase in expressions of Bax and cleaved caspase-3." (PMID 37594700, 2023).
chronic gastritis (3 papers, 2011 to 2020). Inflammation of the stomach that is chronic in nature. "However, in contrast with our findings, the significance of Bcl-2 expression at the stomach has been previously reported and found to be implicated in the multistep process, ranging from chronic gastritis to atrophy, intestinal metaplasia, dysplasia, and finally invasive gastric cancer." (PMID 21822428, 2011). "Bcl-2 is detectable in chronic gastritis but under expressed in advanced and less differentiated GC." (PMID 28662697, 2017).
chronic pancreatitis (3 papers, 2020 to 2025). A chronic inflammatory process causing damage and fibrosis of the pancreatic parenchyma. "To investigate the role of miR-15a in chronic pancreatitis, we first assessed miR-15a levels and its targets (YAP1 and BCL-2) upon the development of chronic pancreatitis in Ptf1aCreERTM and Ptf1aCreERTM;LSL-KRASG12D mice." (PMID 36835366, 2023). "Recent publications have demonstrated that miR-15a, which targets YAP1 and BCL-2, is significantly downregulated in patients with chronic pancreatitis compared to healthy controls." (PMID 36835366, 2023). "Furthermore, the protein level of Bcl-2 and Smad5 in our animal chronic pancreatitis models were detected, and the result showed that Bcl-2 and Smad5 upregulated in chronic pancreatitis model and decreased while treated with SAHA, and negatively correlated with miR-15 or miR-16." (PMID 32524326, 2020). "We demonstrated increased levels of YAP1 and BCL-2 (both targets of miR-15a) in pancreatic tissues obtained from Ptf1aCreERTM and Ptf1aCreERTM;LSL-KrasG12D mice after chronic pancreatitis induction as compared to controls." (PMID 36835366, 2023). "And we proved that Bcl-2 and Smad5 were the target genes of miR-15 and miR-16, which illustrated how HDAC inhibition alleviated the apoptosis and fibrogenesis of PSCs in chronic pancreatitis." (PMID 32524326, 2020).
clear cell carcinoma (3 papers, 2019). "Foci of hobnail cells in MNAC can resemble clear-cell carcinoma, which is characteristically Bcl-2 (+)." (PMID 31266530, 2019).
colonic adenomas (3 papers, 2019 to 2025). "Similar results were demonstrated by a study from 2011, where it was shown that ibuprofen induced both IκBα degradation and nuclear localization of NFκB in human colon adenoma cells, however the activation of NFκB target genes (Bcl-2, survivin, cyclin D1) was suppressed." (PMID 40408503, 2025). "Most colonic adenomas displayed a high level of Bcl-2 protein throughout the neoplastic epithelium while non-neoplastic polyps showed a normal pattern of Bcl-2 expression." (PMID 31108984, 2019).